VTA1 (vesicle trafficking 1)
Description:
Involved in the endosomal multivesicular bodies (MVB) pathway. MVBs contain intraluminal vesicles (ILVs) that are generated by invagination and scission from the limiting membrane of the endosome and mostly are delivered to lysosomes enabling degradation of membrane proteins, such as stimulated growth factor receptors, lysosomal enzymes and lipids. Thought to be a cofactor of VPS4A/B, which catalyzes disassembles membrane-associated ESCRT-III assemblies. Involved in the sorting and down-regulation of EGFR (By similarity). Involved in HIV-1 budding.
Synonyms: DRG-1; LIP5; SBP1; C6orf55; HSPC228; My012; 6orf55
Tractability: Antibody: UniProt places it where antibodies can reach, with high confidence. PROTAC: ubiquitination databases record sites on it; its protein half-life has been measured.
Gene: Protein-coding gene on chromosome 6 (142,147,162 to 142,224,685, forward strand). Ensembl gene ENSG00000009844.
Subcellular location: Cytoplasm; Endosome membrane
Subcellular location (Human Protein Atlas): Cytosol; Nucleoplasm; Vesicles
Pathways (Reactome):
Disease: Budding and maturation of HIV virion
Vesicle-mediated transport: Endosomal Sorting Complex Required For Transport (ESCRT)
Gene Ontology:
Molecular function: protein binding
Biological process: multivesicular body sorting pathway; ESCRT III complex disassembly; late endosome to vacuole transport via multivesicular body sorting pathway; macroautophagy; multivesicular body assembly
Cellular component: cytosol; extracellular exosome; cytoplasm; endosome membrane
Genetic constraint (gnomAD): Loss-of-function variants: 20 observed, 32.36 expected, observed/expected ratio (o/e) 0.62, 90% interval 0.43 to 0.9. The upper end of that interval is the gene's LOEUF score, 0.9, which puts it in group 3 of 6, group 1 being the genes least tolerant of losing a copy. Missense variants: 377 observed, 371.1 expected, observed/expected ratio (o/e) 1.02, 90% interval 0.93 to 1.11. Synonymous variants: 139 observed, 130.64 expected, observed/expected ratio (o/e) 1.06, 90% interval 0.93 to 1.23.
Homologues: Orthologues: chimpanzee VTA1 (100% identical), macaque VTA1 (99% identical), dog VTA1 (95% identical), pig VTA1 (95% identical), rat Vta1 (93% identical), guinea pig VTA1 (93% identical), mouse Vta1 (92% identical), rabbit VTA1 (85% identical), tropical clawed frog vta1 (79% identical), zebrafish vta1 (69% identical), Drosophila melanogaster Vta1 (47% identical).
Diseases named in the same sentence as VTA1 in open-access papers:
VTA1 is named in the same sentence as 3 diseases in open-access papers, as found by Europe PMC text mining. Sharing a sentence is not in itself a finding about the gene and the disease. The quoted sentences say what the papers report.
COVID-19 (2 papers, 2024 to 2025). A disease caused by infection with severe acute respiratory syndrome coronavirus 2. "Molecular characterization of DAZAP2/VTA1/KLF5-knockout cells highlights the involvement of genes related to the coagulation system in determining the severity of COVID-19." (PMID 38168026, 2024).
infection (9 papers, 2014 to 2025). The state of being infected such as from the introduction of a foreign agent such as serum, vaccine, antigenic substance or organism. "In the late phase of infection, although Vps4 and Vta1 were both distributed to the nucleus and at the plasma membrane, depletion of Vta1 did not affect BV release." (PMID 40135896, 2025). "To test this, we first cotransfected Sf9 cells with GFP-LaminBpBlue and the bacmid expressing mCherry or mCherry-tagged Vps4 or Vta1 and examined the subcellular localization of the two proteins at early and late stages of infection." (PMID 40135896, 2025). "Infection of these gRNA-expressing A549-AC lines with SARS-CoV-2 at various MOI conditions produced consistent phenotypes: (i) knocking out pro-viral ATP6V0D1 or DPAGT1 increased cell viability and (ii) knocking out anti-viral DAZAP2, VTA1, or KLF5 decreased cell viability." (PMID 38168026, 2024).
VTA1 also shares sentences with these, for which no sentence is quoted: virus infection (1 paper).